TNF (tumor necrosis factor)
Diseases named in the same sentence as TNF in open-access papers (continued):
Sharing a sentence is not in itself a finding about the gene and the disease.
Sepsis (continued). "Pro‐inflammatory IL‐1β, IL‐6, IL‐8, IL‐12/23p40, TNF‐α, and IFN‐γ, and anti‐inflammatory (regulatory) cytokine IL‐10 play key roles in the acute phase of sepsis." (PMID 41474380, 2026). "We provide evidence that elevated blood lactate levels, due to MAS inactivity contribute to lethality in TNF-induced SIRS by promoting VEGF-mediated vascular leakage, a mechanism that has been unfolded in sepsis." (PMID 41132685, 2025). "The findings revealed a significant elevation in the levels of interleukin-1β (IL-1β), interleukin-6 (IL-6), and tumor necrosis factor-α (TNF-α) in both BALF and serum of sepsis-induced ALI mice." (PMID 41496909, 2025). "Murine sepsis models are characterized by elevated hepatic NK cell levels, and these cells can trigger the release of cytokines including IFN-γ and TNF-α that are capable of triggering the apoptotic death of hepatocytes." (PMID 40061452, 2025). "The release of IL-4 and IL-10 in sepsis suppress Th1 inflammatory response by reducing IFN-γ, TNF-α and IL-1β secretion by Th1 cells and inhibit Th1 cells polarization." (PMID 40364841, 2025). "Elevated levels of senescence-associated secretory phenotype (SASP) markers, including IL-6, IL-1β, and TNF-α, have been detected in mice subjected to cecal ligation and puncture (CLP) to induce sepsis." (PMID 40153575, 2025). "The reduction in the TNF-α and IL-1b by MXF exhibits its protective properties in sepsis and protects the organ damage." (PMID 40327662, 2025). "We observed that enhancing O-GlcNAcylation of FTO using an OGA inhibitor (TMG) decreased LPS-induced TNF-α/IL-1β/IL-6 inflammation and reduced septic mouse mortality, which may constitute a protective mechanism to limit exacerbated inflammation in acute stress conditions such as LPS-induced sepsis." (PMID 40642069, 2025). "Correlation analyses of MAIT cell activation markers and soluble factors in sepsis patients revealed positive, albeit weak, correlations between the MAIT cell CD69 expression and the levels of IL‐12 and IL‐15 and with IFNγ and TNF in the plasma." (PMID 40041474, 2025). "In contrast to the LPS-treated mice, the expressions of the TNFα and IL6 mRNAs were markedly lower in the T0+LPS-treated group, suggesting that LXR protects against sepsis-induced lung injury." (PMID 40994643, 2025). "The potency of phensuximide is that it protects against both LPS- and TNF-induced systemic inflammatory response syndrome (SIRS), which are sepsis models involving RIPK1 kinase activity." (PMID 40456737, 2025). "The cytokine storm is a dangerous hyperinflammatory state associated with elevated levels of several pro-inflammatory cytokines (IL-1β, IL-2, IL-6, IL-17, IL-8, TNF-α) and chemokine L2 (CCL2) and it is an integral part of sepsis." (PMID 40650213, 2025). "The treatment significantly reduced serum levels of key biomarkers of sepsis, including C-reactive protein (CRP), lactate (Lac), tumor necrosis factor-alpha (TNF-α) and interleukin-6 (IL-6), and dose-dependently improved the survival of septic mice." (PMID 41157235, 2025). "In mice with LPS-induced sepsis, myocardial TLR4 and JNK protein expression, plasma TNF-α and cTnI levels, and cardiac dysfunction are elevated." (PMID 40640887, 2025). "Serum levels of IL-6, TNF-α, IL-1β, and HMGB1 were markedly elevated in sepsis groups compared to Sham (P < 0.001)." (PMID 41281995, 2025). "Many proinflammatory cytokines, such as IL-1, IL-6, IL-8, IL-12, IL-18, TNF-a, and IFN-r, are highly expressed, leading to cytokine storms after sepsis develops." (PMID 40136690, 2025).
Sepsis (continued). "At early stage of sepsis, referred to as systemic hyperinflammatory response syndrome (SIRS), cytokines including tumor necrosis factor α (TNF‐α), interleukin (IL)‐1, IL‐2, IL‐6, are significantly elevated, which results in aberrant STAT3 activation." (PMID 41042728, 2025). "In pathological conditions, such as sepsis and ARDS, M1 macrophages contribute to alveolar barrier disruption by secreting TNF-α and IL-1β, which increase vascular permeability and promote leukocyte recruitment." (PMID 41488672, 2025). "Sepsis triggers a systemic inflammatory response syndrome (SIRS), characterized by the release of pro-inflammatory cytokines such as tumor necrosis factor-alpha (TNF-α), interleukin-6 (IL-6), and interleukin-1β (IL-1β)." (PMID 41425961, 2025). "XBJ exerted therapeutic effects on sepsis and septic-AKI through suppression IL-1β/MMP9, IL-6/MMP9 and TNFα/MMP9 at both mRNA and protein level." (PMID 41042728, 2025). "Tumor necrosis factor-alpha (TNF-α), a central mediator of sepsis produced by macrophages and other immune cells, induces endothelial dysfunction, coagulopathy, and organ failure through inflammatory cascades." (PMID 41196905, 2025). "It has been previously shown that Sirt1 is downregulated in macrophages in preclinical models of sepsis and may play a role in orchestrating innate immune activation, particularly through the activation of NF-κB and the subsequent production of pro-inflammatory cytokines such as IL-6 and TNF-α." (PMID 41096578, 2025). "We also found a reduction in TNF‐α and CXCL1 levels in the plasma and peritoneum of bosutinib‐treated mice with sepsis." (PMID 40292988, 2025). "Studies in sepsis models revealed that TREM-1 knockout mice express lower levels of IL-6, TNFα, and IL-1β compared to wild-type mice after eCIRP injection." (PMID 40332009, 2025). "Genetic attenuation of ADAM17 in myeloid cells or hepatocytes reduces circulating TNF-α levels and improves survival following LPS challenge, while small-molecule ADAM17 inhibitors have demonstrated anti-inflammatory effects in sepsis models." (PMID 41465816, 2025). "Adhesion burden, neutrophil-rich infiltration, fibrosis, and neovascularization were all heightened with sepsis and were consistently attenuated by NAC, while circulating IL-6 and TNF-α fell below control levels under NAC exposure." (PMID 41440550, 2025). "A meta-analysis of clinical trials using DEX to treat sepsis patients in intensive care units (ICU) found that its use significantly reduced IL-6, TNF-α and overall mortality." (PMID 41124072, 2025). "Decreased TBARS and TNF-α levels and increased total thiol levels in the lung tissue of CLP-induced sepsis rats are consistent with the literature data, showing that our sepsis model works and that sepsis-related lung damage has occurred." (PMID 39860018, 2025). "Tumor Necrosis Factor-Alpha (TNF-α): A key inflammatory mediator contributing to immune system activation and sepsis progression." (PMID 40296930, 2025). "Serum Lac, PLT, TBA, BUN, D-dimer, TNF-α levels of the early stage of sepsis, pH, Glu, ALB, TBA, CK-MB, PCT, and TNF-α levels of the serious stage of sepsis and complications with statistically significant differences were verified by the ROC curve." (PMID 39266629, 2025). "This tug-of-war involves not just IL-6, but a chorus of markers, like tumor necrosis factor-alpha (TNF-α), which kickstarts the cytokine storm, and C-reactive protein (CRP), a downstream signal of inflammation, all shaping sepsis’s chaotic course." (PMID 40149943, 2025). "This systemic inflammation is prevalent in sepsis, and is characterized by elevated inflammatory markers such as C-reactive protein (CRP), tumor necrosis factor-alpha (TNF-α), and interleukin-6 (IL-6)." (PMID 40098009, 2025). "The data obtained from clinical patients revealed elevated levels of multiple cytokines (such as IL-1, TNF-a, IL-8 and HMGB1) in the CSF following sepsis." (PMID 39473252, 2025).
Sepsis (continued). "Recent investigations in sepsis, ARDS, and COVID-19 have consistently shown that integrating IL-6 with cytokines, such as IL-8, TNF-α, and IL-10, enhances discrimination for mortality, organ failure, and disease severity." (PMID 41155261, 2025). "In mice, exenatide and semaglutide reduce plasma TNF-α levels induced by agonists for TLR1, TLR2, TLR4, TLR5, and TLR9 or by cecal slurry–induced polymicrobial sepsis." (PMID 41178710, 2025). "Sepsis also triggers an SIRS, marked by the release of proinflammatory cytokines such as IL-6 and tumor necrosis factor-alpha." (PMID 40546531, 2025). "Statistical analysis was performed on serum concentrations of CRP, IL-6, IL-1β, TNF-α, IL-10, and PDL1 from healthy individuals and sepsis patients, using a 95% CI." (PMID 40568710, 2025). "It is of relevance to the effective management of sepsis that the NTCI peptide suppressed the mediators of inflammation in the blood (IL-6, IL-10, TNFα, Interferon γ, and MCP1)." (PMID 41229427, 2025). "Studies have demonstrated that C-reactive protein, procalcitonin, tumor necrosis factor α, interleukin-6, and neutrophil surface receptors (CD64) are currently widely utilized as biomarkers for monitoring sepsis." (PMID 40867545, 2025). "Subsequently, we measured the mRNA expression of SLC25A22, SLC25A33, and SLC25A37, along with that of pro-inflammatory cytokines, including TNF-α, IL-6, and IL-1β, in CD14+ monocytes from sepsis patients with liver abscesses." (PMID 40384854, 2025). "Unsurprisingly, serum cytokines (TNF-α, IL-6, and IL-10) in probiotic-treated CLP sepsis mice were lower than in the untreated CLP group." (PMID 41444762, 2025). "We next focused on proinflammatory cytokines that play a major role in sepsis, including IFN-γ, TNFα, IL-6, and IL-1β." (PMID 40510337, 2025). "This study was designed to assess the value of serum cystatin-C levels and genetic determinants, such as TNF-α (−238, rs361525), for predicting and diagnosing S-AKI development in critically ill patients with sepsis." (PMID 40724987, 2025). "In the initial hit phase, the sepsis-induced systemic inflammatory response syndrome (SIRS) triggers a significant release of pro-inflammatory cytokines, particularly TNF-α, IL-1β, and IL-6." (PMID 41451099, 2025). "Compared with the Sepsis group, the Cur + Sep group showed significantly lower Paller damage scores, reduced Scr, BUN, TNF‐α, IL‐1β, IL‐6, MDA, Fe2+ levels, and ACSL4 protein expression (all p < 0.05)." (PMID 41140036, 2025). "LPS stimulates monocytes to secrete a large amount of TNF-α, which leads to a significant increase in the concentration of serum TNF-α in sepsis patients." (PMID 40529149, 2025). "When comparing SIRS and Sepsis_A patients, higher concentrations were observed in the latter group for Azurocidin (p = 0.0137), PCT (p = 0.0114), IL-8 (p = 0.0153), TNF-α (p = 0.0192), and IL-35 (p < 0.0001)." (PMID 41301767, 2025). "Recently, it was described that the pairwise combination of tumor necrosis factor (TNF) with IL-18, interferon-gamma (IFN-gamma), or IL-1beta recapitulates most of the cellular transcriptional signatures of sepsis across dysfunctional organs." (PMID 40241761, 2025). "Evaluation of the mouse sepsis model indicated that Abs-9 had a prophylactic protective effect against S. aureus infection and upregulating the levels of CCL3 and TNF-α." (PMID 39834865, 2025). "These elevated eCIRP levels, observed in the context of these inflammatory diseases, induce macrophage production of TNF-α, IL-1β, and IL-6, contributing to multi-organ dysfunction, including ALI and acute kidney injury (AKI) in sepsis." (PMID 40332009, 2025). "MV were isolated from supernatants of TNFα-stimulated primary human pulmonary microvascular endothelial cells (HPMEC) and plasma from 20 sepsis patients by ultracentrifugation and quantified using flow cytometry." (PMID 40950553, 2025).
Sepsis (continued). "In this context, the present study aims to establish a predictive model for the occurrence of SAE in sepsis patients based on the combination of IFN-γ, TNF-α and the CD4+/CD8+ ratio." (PMID 41189156, 2025). "The proliferation of cytokines such as TNF-α, INF-γ, IL-6, and IL-8 have been identified in humans but are typically dependent on wound size and the presence of sepsis." (PMID 40843802, 2025). "Next, we studied TNF‐α and CXCL1 levels in mice with CLP‐induced sepsis and how bosutinib treatment influences those levels in the plasma and peritoneum of septic mice." (PMID 40292988, 2025). "Studies in sepsis animal models have shown that reducing ADAM17 expression decreases serum levels of IL-1β, IL-6, and TNF-α while also decreasing ICAM-1 and VCAM-1 expression in lung and liver tissues, thereby significantly improving 72-h survival in mice." (PMID 41280722, 2025). "High-dose levosimendan significantly reduced TNF-α, IL-1β, IL-6, and MCP-1 levels by the 10th hour, accompanied by improved Murine Sepsis Scores." (PMID 40566580, 2025). "Inflammatory mediators that are commonly elevated during the acute phase of sepsis include interleukins (IL)-1β, IL-6, IL-8, CC motif chemokine ligand 2 (CCL2) and tumour necrosis factor (TNF)-α." (PMID 41124072, 2025). "C57BL/6 male mice with a global or macrophage-specific Clock or Per2 deletion release fewer cytokines, including tissue necrosis factor-α (TNFα) and interleukins, in settings of LPS- or CLP-induced sepsis." (PMID 39968295, 2025). "In the CLP-induced sepsis kidney injury model, the IL-2 gene exhibited low expression, whereas the CXCL8, IL-1β, TNF, IL-6, and IL-10 genes demonstrated high expression levels." (PMID 40166075, 2025). "To further delineate the effects of sepsis on PLN T cells in MLDS T1D, we determined the number of CD4+ and CD8+ T cells able to produce IFN-γ, IL-17, TNF and IL-10 in CLP+STZ and SHM+STZ mice." (PMID 41142792, 2025). "The MAIT cell‐activating cytokines IL‐12, IL‐15 and IL‐18, as well as TNF, IFNγ and IL‐17A, cytokines known to be produced by MAIT cells, were elevated in the plasma of sepsis patients as well as non‐sepsis patients, compared with non‐infected controls." (PMID 40041474, 2025). "Plasma levels of IL‐12, IL‐15, TNF, IFNγ and CXCL10 correlated with the magnitude of MAIT cell activation in sepsis patients." (PMID 40041474, 2025). "Another study, which enrolled 3,250 subjects, found that serum concentrations of IL-1β, TNF-α, and interferon (IFN)-γ were elevated in patients with sepsis." (PMID 38558800, 2024). "To evaluate the effect of prematurity on the production of TNF-α and IL-6, we exposed preterm neonatal, term neonatal and adult WB to TLR ligands and sepsis-related bacteria." (PMID 38562936, 2024). "Sepsis induces an up-regulation in the production of proinflammatory cytokines, including IL1-β, IL-6, and TNF-α." (PMID 38629103, 2024). "GSEA of the gene sets for the Toll-like receptor, TNF, and NOD-like receptor signalling pathways revealed that these gene sets were highly enriched in the sepsis groups." (PMID 38169584, 2024). "Several protein biomarkers have already been proposed as prognostic markers of sepsis, such as CRP, lipopolysaccharide binding protein, PCT, or cytokines such as tumor necrosis factor-α and interleukin-6." (PMID 39335614, 2024). "At higher concentrations, they stimulate an over-production of proinflammatory cytokines such as tumor-necrosis factor alpha (TNF-α) or interleukins such as IL-1 and IL-6 and can lead to sepsis or multi-organ failure." (PMID 38612737, 2024). "We developed a nomogram model to predict the incidence of NOAF during sepsis, incorporating MPO, HOCl, TNF-α, WBC, and APACHE II score." (PMID 39030470, 2024). "In our study, the occurrence of early infectious complications in the anti-TNF group was similar to that of the PUCCINI study (22.8%, when combining infections and sepsis)." (PMID 38305302, 2024).
Sepsis (continued). "Collectively, the data implicate central PI3K/MAPK/TNFα signaling in the A3AR counteraction of the ameliorative action of nicotine on cardiovascular and neuroinflammatory derangements in sepsis." (PMID 38966542, 2024). "Conversely, the expression levels of pro-apoptotic and pro-inflammatory markers Caspase-3, P2X7R, TLR4, IL-1β, and TNF-α were found to be significantly escalated in the CLP group, which was indicative of the potent inflammatory response triggered by sepsis." (PMID 38546748, 2024). "In the inflammatory landscape of sepsis, markers like P2X7R, TLR4, IL-1Β, and TNF-α take center stage." (PMID 38546748, 2024). "A concentration-dependent production of TNF-α and IL-6 was observed after exposure of term neonatal or adult WB to different TLR ligands and sepsis-related bacteria." (PMID 38562936, 2024). "In septicemia, inhibiting PLD enzymatic activity reduced PLD-mediated cell adhesion and migration, resulting in lowered TNF-α levels in septic mice plasma and reduced migration of leukocytes and platelets to the lungs." (PMID 38572075, 2024). "anshinol treatment in a rat sepsis model has been demonstrated to significantly increase AQP5 mRNA expression and reduce inflammatory cytokines IL-6 and TNF-α." (PMID 39544938, 2024). "As expected, IL-4, IL-6, IL-10, IL-17, TNF-α, and CCL2 were significantly elevated from the early stage of sepsis, but on CLP day 6, all cytokines were reduced to levels similar to those of sham mice." (PMID 38385073, 2024). "We found that the levels of IL-6, TNF-α, and IL-10 in the serum were upregulated in CLP-induced sepsis mice than those in sham group." (PMID 37776443, 2024). "Cmtm3 KO reduced the release of TNF-α, IL-1β, and IL-10 in the peripheral blood of CLP-induced sepsis mice, while TLR4 overexpression reversed this protective effect." (PMID 39455728, 2024). "In sepsis, the hypermethylation of genes involved in immune activation, such as interferon-gamma (IFN-γ) and tumor necrosis factor-alpha (TNF-α), contributes to immune paralysis by silencing pro-inflammatory pathways essential for pathogen clearance." (PMID 39594987, 2024). "In our study, we observed a significant increase in NO levels and pro-inflammatory cytokines IL-1β, IL-6, and TNF-α in the serum of mice with CLP- and LPS-induced sepsis." (PMID 39337575, 2024). "Our results showed that the anti-PD-L1 antibody markedly decreased the level of serum inflammatory cytokines interleukin (IL)-6, tumor necrosis factor (TNF)-α, and IL-10 in sepsis mice at 24 h, 48 h, and 72 h, respectively (P < 0.05)." (PMID 37776443, 2024). "Five of the eleven biomarkers (IL-6, TNF-α, IL-8, IL-10, and sST-2) were significantly higher in patients with GN sepsis or NEC than those with NS, CS, and GP sepsis (p < 0.05)." (PMID 38312920, 2024). "Unsurprisingly, the levels of IL-1β, TNF-α, and IL-6 produced by TREM2+ monocytes were positively correlated with serum triglyceride concentrations of sepsis patients." (PMID 39405126, 2024). "Our data support a model whereby a few elements of cytokine information—TNF plus IL-18, IFN-γ or IL-1β—suffice to explain a large fraction of the molecular and cellular effects of sepsis across tissues." (PMID 38191855, 2024). "In a CLP surgery-induced sepsis model of mice, the administration of 5–20 g/kg of the QX1 decoction reduced sepsis-induced upregulated levels of serum IFN-γ, IL-1β, IL-3, IL-6, IL-17, IL-4, IL-10 and TNF-α." (PMID 39051370, 2024). "We observed that the upregulated genes were enriched mainly in classic signaling pathways related to sepsis, including apoptosis, MAPK, PD-1, PI3K-Akt, and TNF signaling pathways." (PMID 38909272, 2024). "The effects of TNF plus IL-18, IFN-γ or IL-1β encompassed a high proportion of sepsis biomarker genes, 45.7% (118/258), 43.8% (113/258) or 32.6% (84/258), respectively, compared to the other 12 cytokine pairs tested (8.1% ± 7.3% s.d.)." (PMID 38191855, 2024).